AKR1B10 (aldo-keto reductase family 1 member B10)
Diseases named in the same sentence as AKR1B10 in open-access papers (continued):
Sharing a sentence is not in itself a finding about the gene and the disease.
cervical cancer (3 papers, 2021 to 2025). A primary or metastatic malignant neoplasm involving the cervix. "Recent research mainly focused on specific cell types and signaling pathways in the cervical cancer TME, such as EPCs and their associated pathways (e.g., TSPAN1, AKR1B10), while studies on other cell types and molecular mechanisms were relatively scarce." (PMID 40777026, 2025).
colitis (3 papers, 2022 to 2024). Inflammation of the colon. "Therefore, the focus of this study was to test the response of AKR1B8 KO mice to acute colitis induced by DSS in order to address the potential pathogenic role of AKR1B10 in human colitis." (PMID 36518763, 2022). "Surprisingly, cKit- FcεRI+ basophils in the acute colitis exclusively increased up to 58.1% in AKR1B10 KO mice vs. 1.4% in wild type; the absolute number of cKit- FcεRI+ basophils increased over 100 times in AKR1B10 KO mice compared to wild type)." (PMID 36518763, 2022). "Thus, we generated aldo-keto reductase 1B8 (AKR1B8, the ortholog of human AKR1B10) knockout mice to explore its potential etiopathological role in colitis." (PMID 36518763, 2022).
colon adenocarcinoma (3 papers, 2021 to 2025). "The AKR1B10 expression was markedly down-regulated in metastatic lesions compared to primary tumors, as evidenced by analyses of the colon adenocarcinoma (COAD)–GEO dataset and our independent cohort." (PMID 40845116, 2025). "Moreover, in bladder urothelial carcinoma (BLCA), colon adenocarcinoma (COAD), kidney chromophobe (KICH), kidney renal clear cell carcinoma (KIRC), rectum adenocarcinoma (READ), and stomach adenocarcinoma (STAD), AKR1B10 expression levels showed a decreasing trend compared to normal tissues." (PMID 38802416, 2024).
diabetic nephropathy (3 papers, 2016 to 2023). "The evidence that AKR1B10 is involved in inflammatory responses has been confirmed in diabetic nephropathy (DN)." (PMID 37039038, 2023). "The significantly higher expression of AKR1B10 in peripheral blood mononuclear cells (PBMCs) in diabetic nephropathy patients vs. healthy controls suggests that AKR1B10 mediates the development and progression of diabetic nephropathy." (PMID 30320113, 2018). "Moreover, Akr1b10 has been shown to be inducible by hyperglycemia in peripheral blood mononuclear cells obtained from patients with diabetic nephropathy." (PMID 27496100, 2016).
glioma (3 papers, 2019 to 2024). A benign or malignant brain and spinal cord tumor that arises from glial cells (astrocytes, oligodendrocytes, ependymal cells). "Our study shows that high motility gliomas expressing Cx43 differ from their parental counterparts by the upregulation of MMP3, osteopontin, aldo-keto reductase family 1 member B10 (ARK1B10), and to a lesser degree SERPINE2 (2.5-fold, P = 0.03), and phosphoglycerate kinase 1 (2.4-fold, P = 0.04)." (PMID 30941001, 2019). "While, AKR1B10 was not specifically expressed in BM tissue, since the expression in brain metastases was not significantly different from NSCLC without BM and glioma tissues." (PMID 35217799, 2022).
keloid (3 papers, 2021 to 2024). An irregularly shaped, elevated mark on the skin caused by deposits of excessive amounts of collagen during wound healing. "The AKR1B10-overexpressing keratinocytes also secrete paracrine signals that enhance the fibrogenic activity of dermal fibroblasts and contribute to keloid pathobiology." (PMID 34063865, 2021). "In particular, AKR1B10, revealed to be a differentially overexpressed gene in keloids through the whole-genome microarray analysis of lesions and normal tissue, and GDF-9, discovered through analysis using a TGF-β superfamily signaling gene chip, are attractive therapeutic targets." (PMID 38279232, 2024). "A laser capture microdissection-based whole-genome microarray analysis discovered that AKR1B10 is highly upregulated in the keloid epidermis, suggesting that the altered metabolism of retinoic acid may be associated with keloid pathogenesis." (PMID 38279232, 2024).
liver cirrhosis (3 papers, 2017 to 2019). "AKR1B10 gene expression was significantly higher in HCC with liver cirrhosis (n = 22) and tumor-free cirrhotic liver samples (n = 22)." (PMID 30959792, 2019). "A small sample study demonstrated that increased expression of AKR1B10 in moderately-differentiated HCC compared with well-differentiated HCC, poorly-differentiated HCC, and liver cirrhosis." (PMID 31598161, 2019). "A recent study confirmed increased AKR1B10 expression in early-stage HCC and showed higher AKR1B10 expression in moderately differentiated HCC compared with well-differentiated HCC, poorly differentiated HCC, and liver cirrhosis." (PMID 30959792, 2019).
lung squamous cell carcinoma (3 papers, 2020 to 2024). "Furthermore, higher AKR1B10 expression has been observed in squamous cell lung carcinoma (SCC) associated with smoking." (PMID 32097409, 2020).
melanoma (3 papers, 2016 to 2022). A malignant, usually aggressive tumor composed of atypical, neoplastic melanocytes. "Using publicly available expression data of melanoma cells treated with the MLN4924 inhibitor, we confirmed significant upregulation of NRF2 target genes, including AKR1B10 as one of the most significantly upregulated genes." (PMID 36068196, 2022). "Consistent with previous reports that associated the Nrf2 pathway with SFN-induced chemoprevention, we found that the Nrf2 target genes HMOX1, TXNRD1, GCLC, GCLM, AKR1B10 and G6PD were upregulated after melanoma treatment." (PMID 28864908, 2018).
non-alcoholic fatty liver disease (3 papers, 2021 to 2022). "Moreover, AKR1B10 shows close association with the immune cell infiltrations and in non-alcoholic fatty liver disease." (PMID 36028503, 2022). "In contrast, AKR1B10 expression is low in other tissues, where the enzyme is upregulated in cancers, as well as in non-alcoholic fatty liver disease and several skin diseases." (PMID 34063865, 2021). "We found several blood biomarkers through computational secretome analyses, including aldo-keto reductase family 1 member B10 (AKR1B10), which reflected the progression of nonalcoholic fatty liver disease (NAFLD)." (PMID 35563425, 2022).
nonalcoholic steatohepatitis (3 papers, 2022 to 2023). "After confirming that hepatic AKR1B10 reflected the progression of NAFLD in a subgroup with NAFLD, we evaluated the diagnostic accuracy of plasma AKR1B10 and other biomarkers for the diagnosis of nonalcoholic steatohepatitis (NASH) and fibrosis in replication cohort." (PMID 35563425, 2022).
ovarian carcinoma (3 papers, 2022 to 2025). A malignant neoplasm originating from the surface ovarian epithelium. "AKR1B10 (upregulated in MBL) plays a key role in cancer via lipid metabolism, and has been shown to be a prognostic biomarker in breast and ovarian cancers." (PMID 40778374, 2025). "AKR1B10 has been shown to increase FAO in metastatic breast cancer, and the inhibition of AKR1C1/2 can sensitize platinum‐resistant ovarian cancer toward carboplatin." (PMID 39924751, 2025). "Until now, no study has assessed AKR1B1 and AKR1B10 levels using IHC in a large cohort of ovarian cancer patients." (PMID 35159076, 2022).
prostate carcinoma (3 papers, 2019 to 2024). A carcinoma that arises from epithelial cells of the prostate gland. "Both members of the aldo-keto reductases (AKRs) family, AKR1B1 and AKR1B10, are over-expressed in various type of cancer, making them potential targets for inflammation-mediated cancers such as colon, lung, breast, and prostate cancers." (PMID 35807227, 2022).
viral hepatitis (3 papers, 2016 to 2023). An acute or chronic inflammation of the liver parenchyma caused by viruses. "AKR1B10 expression is also associated with viral hepatitis and HCC risk." (PMID 30959792, 2019).
adrenocortical carcinoma (2 papers, 2021 to 2024). "Aldo-Keto Reductase Family 1 Member B10 (AKR1B10) and Homeobox A5 (HOXA5) are both down-regulated in adrenocortical carcinoma (ACC), and HOXA5 is predicted to bind to the promoter of AKR1B10." (PMID 34027794, 2021).
coronavirus disease 2019 (2 papers, 2022 to 2023). "The analysis of transcriptome data of lung samples from coronavirus disease 2019 (COVID-19) patients showed that the expression of the gene encoding AKR1B10 was increased." (PMID 37039038, 2023).
Endometrioid Endometrial Carcinomas (2 papers, 2021 to 2022). "It is also unclear why AKR1B10, which plays a protective role in endometrioid endometrial carcinomas and is also induced by NRF2 signaling, does not exert protective effects in HGSC." (PMID 35159076, 2022).
gynecological cancer (2 papers, 2022 to 2024). "AKR1B10 is expressed in many organs and it has also been studied in a variety of cancers, such as in liver, lung, gynecological cancer, and breast." (PMID 36661656, 2022).
hepatitis B (2 papers, 2014 to 2018). "The present study showed that AKR1B10 expression in NTs was not significantly different according to hepatitis B or C viral infection status." (PMID 24747592, 2014).
leiomyoma (2 papers, 2020 to 2022). A well-circumscribed benign smooth muscle neoplasm characterized by the presence of spindle cells with cigar-shaped nuclei, interlacing fascicles, and a whorled pattern. "To evaluate the expression of AKR1B10 in histopathological leiomyoma variants, we screened 141 FFPE variant tumors by immunohistochemistry." (PMID 36068196, 2022). "Indeed, we recently analyzed publicly available leiomyoma data and reclassified two leiomyomas as FH-deficient partly based on the expression of AKR1B10." (PMID 36068196, 2022). "This suggests that these AKR1B10 overexpressing tumors represent a novel leiomyoma subtype." (PMID 36068196, 2022). "However, high expression of AKR1B10 was observed in two fresh frozen samples that were originally classified as HMGA1 overexpressing leiomyomas." (PMID 33352722, 2020). "In addition, we identified AKR1B10 expression in nine leiomyomas with no indication of FH-deficiency or alterations affecting MED12 or HMGA2." (PMID 36068196, 2022). "Leiomyomas of the FH subtype are characterized by activation of the NRF2 pathway, including upregulation of the NRF2 target gene AKR1B10." (PMID 36068196, 2022). "Leiomyomas of the FH subtype are characterized by activation of nuclear factor, erythroid 2 like 2 (NRF2) target genes, including upregulation of aldo-keto reductase family 1 member B10 (AKR1B10) and NAD(P)H quinone dehydrogenase 1 (NQO1)." (PMID 36068196, 2022).
metastatic diseases (2 papers, 2022 to 2024). "ROC plotting analyses demonstrated that the serum AKR1B10 was a promising diagnostic marker with high sensitivity and specificity in both localized and metastatic diseases." (PMID 35280770, 2022). "Therefore, our study results do not support the serum AKR1B10 as a marker of the disease burden in metastatic diseases." (PMID 35280770, 2022).
oral cancer (2 papers, 2017 to 2024). "Cigarette smoke has been shown to induce cytochrome P450 (CYP1A1, CYP1B1) and aldo-keto reductase (AKR1C1, AKR1C3, AKR1B10) genes in oral dysplasia and primary oral carcinoma cell lines." (PMID 28467356, 2017).
severe acute respiratory syndrome (2 papers, 2022 to 2025). A viral respiratory infection caused by the SARS coronavirus. "Notably, AKR1B10 is a key enzyme involved in the expression of pro-inflammatory cytokines in SARS-CoV2 Severe Acute Respiratory Syndrome." (PMID 40455785, 2025).
brain tumours (1 paper, 2022). "The clinical value of CTSF, FBLN1, and AKR1B10 in the diagnosis of NSCLC BM was assessed in cohort 2 comprising of 459 patients including 379 patients with NSCLC, 30 primary brain tumours (PBT), and 50 HG." (PMID 35217799, 2022).
breast diseases (1 paper, 2022). "There is a paucity of data on the use of either CA15.3 or CA27.29 in the diagnosis of DCIS/LCIS, and our data indicates that AKR1B10 is elevated in these premalignant conditions, being a potential marker for clinical management of the premalignant breast diseases." (PMID 35280770, 2022).
chronic obstructive pulmonary disease (1 paper, 2022). A chronic and progressive lung disorder characterized by the loss of elasticity of the bronchial tree and the air sacs, destruction of the air sacs wall, thickening of the bronchial wall, and mucous accumulation in the bronchial tree. "Indeed, Chronic Obstructive Pulmonary Disease (COPD), various types of cancer, diabetes, and Non-Alcoholic Fatty Liver Disease (NAFLD), strongly associated with type II diabetes, are conditions associated with both high AKR1B10 expression and a high proportion of severe COVID-19 forms." (PMID 35163833, 2022).
colorectal tumours (1 paper, 2022). "An interesting corollary of our study is the unexpected downregulation of AKR1B10 and AKR1C1 expression in human colorectal tumours." (PMID 35204145, 2022).
invasive carcinoma (1 paper, 2018). A carcinoma that is not confined to the epithelium, and has spread to the surrounding stroma. "In pancreatic ductal neoplasms, AKR1B10 is overexpressed in precursor lesions and invasive carcinoma." (PMID 30320113, 2018).
kidney tumor (1 paper, 2023). "Using IHC data from the Protein atlas database, we observed strong or moderate staining for ACAA2, ACAT1, ASRGL1, and AKR1B10, weak staining for ANGPTL4 and ABCC2 in normal kidney tissues and opposite staining results in kidney tumor samples." (PMID 36829161, 2023).
laryngeal carcinoma (1 paper, 2021). Carcinoma that arises from the laryngeal epithelium. "AKR1B10 protein expression was higher in laryngeal carcinoma than in the adjacent squamous epithelium." (PMID 34521883, 2021). "This study was the first to detect the expression of AKR1B10 in laryngeal carcinoma and explore its relationship with tumor differentiation, tumor size, lymph node metastasis and prognosis." (PMID 34521883, 2021). "AKR1B10 expression in laryngeal carcinoma cells was mainly localized in the cytoplasm, and the individual nuclei also displayed positive staining." (PMID 34521883, 2021). "We plan to perform in vivo experiments to further study the role of AKR1B10 in laryngeal cancer in the future." (PMID 34521883, 2021). "Whether AKR1B10 directly or indirectly promotes the occurrence and metastasis of laryngeal cancer through MMP2 remains to be further studied." (PMID 34521883, 2021). "AKR1B10 was overexpressed in Hep-2 laryngeal carcinoma cells." (PMID 34521883, 2021). "Based on the findings, AKR1B10 may represent a new target and theoretical molecular basis for the treatment and prognosis of laryngeal cancer." (PMID 34521883, 2021). "We hypothesized that AKR1B10 overexpression may be involved in the development and progression of laryngeal cancer." (PMID 34521883, 2021). "However, we found that AKR1B10 is upregulated in laryngeal carcinoma, and its expression was negatively correlated with the degree of differentiation." (PMID 34521883, 2021). "In addition, AKR1B10 is diffusely expressed in laryngeal carcinoma cells." (PMID 34521883, 2021). "Therefore, AKR1B10 may be related to the development of laryngeal carcinoma, suggesting its use as a prognostic indicator for laryngeal cancer." (PMID 34521883, 2021). "Therefore, we speculate that the overexpression of AKR1B10 in laryngeal carcinoma may be related to the occurrence and poor prognosis of cancer." (PMID 34521883, 2021). "Among 87 laryngeal carcinoma tissues, 51 were AKR1B10+ MMP2+, 14 were AKR1B10− MMP2−, 5 were AKR1B10+ MMP2−, and 17 were AKR1B10− MMP2+." (PMID 34521883, 2021). "Therefore, we speculate that AKR1B10 could be an indicator of poor prognosis in laryngeal cancer." (PMID 34521883, 2021). "This study analyzed the expression of AKR1B10 in LSCC and the correlations of its expression with laryngeal carcinoma differentiation, tumor size, lymph node metastasis, and prognostic indices." (PMID 34521883, 2021). "At present, studies on the expression of AKR1B10 in laryngeal cancer have not been reported." (PMID 34521883, 2021). "However, studies on AKR1B10 expression in laryngeal carcinoma have not been reported." (PMID 34521883, 2021).
leukaemias (1 paper, 2020). "AKR1B10 is also significantly overexpressed in several leukaemias; therefore, the implications of its targeting by ibrutinib should be further evaluated." (PMID 33322571, 2020).
metastasis (1 paper, 2016). The spread or migration of cancer cells from one part of the body (where they first appeared) to another. "Our results showed that AKR1B10 expression levels are negatively correlated with tumor types, neck masses, and lymph node metastasis of NPC, and positively correlated with NPC differentiation." (PMID 26949513, 2016).
pancreatic adenocarcinoma (1 paper, 2024). "In pancreatic adenocarcinoma cell lines, siRNA-knockdown of AKR1B10 induced apoptotic cell death associated with decreased expression of the membrane-bound prenylated protein, KRAS." (PMID 39055885, 2024). "AKR1B10 was found to be upregulated in pancreatic adenocarcinomas and pancreatic intraepithelial neoplasia." (PMID 39055885, 2024).
pterygium (1 paper, 2022). A wedge-shaped fibrovascular lesion arising from the bulbar conjunctiva and extending to the cornea. "Among those DE-mRNAs, matrix metallopeptidase 3(MMP-3), fibronectin 1 (FN1), tenascin C (TNC), LRRC15, KRT6A, COMP, AKR1B10, and MUC5AC were significantly upregulated, which was consistent with previous studies on pterygium." (PMID 36398070, 2022).
renal carcinoma (1 paper, 2017). A carcinoma arising from the epithelium of the renal parenchyma or the renal pelvis. "Increased expression of proteins involved in sex steroid inactivation (AKR1C1, AKR1C2, AKR1C3, AKR1B10) in DIO1 re-expressing renal cancer cells might indicate decreased local production of androgens, which have been linked to proliferation of renal and other cancers expressing androgen receptor." (PMID 29272308, 2017).
rheumatoid arthritis (1 paper, 2024). A chronic, systemic autoimmune disorder characterized by inflammation in the synovial membranes and articular surfaces. "In this study, we employed bioinformatics and machine learning techniques to identify seven key genes associated with rheumatoid arthritis (RA): AKR1B10, MMP13, FABP4, NCF1, SPP1, COL1A1, and RASGRP1." (PMID 39430588, 2024).
serous ovarian cancer (1 paper, 2022). "We evaluated the levels of AKR1B1 and AKR1B10 in 99 patients with high-grade serous ovarian cancer and their association with clinicopathological characteristics, survival, and response to chemotherapy." (PMID 35159076, 2022). "We assessed the immunohistochemical levels of AKR1B1 and AKR1B10 in tissue paraffin sections from 99 patients with high-grade serous ovarian cancer (HGSC) and compared these levels with clinicopathological characteristics, survival, and response to chemotherapy." (PMID 35159076, 2022). "We used the RNA expression data of the genes AKR1B1 and AKR1B10 in the tissues of high-grade serous ovarian cancer (acquired by RNA-Seq and Expectation-Maximization (RSEM) algorithms with batch normalization) and clinical data from the TCGA Pan-Cancer Atlas study." (PMID 35159076, 2022).
signet ring cell carcinoma (1 paper, 2022). A usually aggressive, poorly differentiated invasive adenocarcinoma characterized by the presence of malignant glandular cells in which the nucleus is pressed to one side by the presence of intracytoplasmic mucus. "For 162 stage II or III patients who received adjuvant chemotherapy after surgical resection and 59 patients with signet ring cell carcinoma histology, AKR1B10 overexpression was also associated with inferior DFS and OS." (PMID 36661656, 2022).
thymoma (1 paper, 2013). A neoplasm arising from the epithelial cells of the thymus. "The expression levels of AKR1B10 are low (unpublished data) in IU-TAB-1 cell line, established by our group from a patient with stage II thymoma, WHO type AB." (PMID 23894276, 2013).